SKA1 (spindle and kinetochore associated complex subunit 1)
Diseases named in the same sentence as SKA1 in open-access papers (continued):
Sharing a sentence is not in itself a finding about the gene and the disease.
SKA1 also shares sentences with these, for which no sentence is quoted: Papillary Thyroid Carcinoma (2 papers); bladder cancer (1); Breast (1); colon cancer (1); colorectal cancer (1); Ductal Carcinoma (1); liver cancer (1); melanoma (1); oral squamous cell carcinoma (1); prostatic intraepithelial neoplasia (1).